HIF1A (hypoxia inducible factor 1 subunit alpha)
Diseases named in the same sentence as HIF1A in open-access papers (continued):
Sharing a sentence is not in itself a finding about the gene and the disease.
cervical carcinoma (continued). "However, in most of the tumor samples investigated, CAIX seems to be upregulated by HIF-1; CAIX(−)/HIF-1α (+) and CAIX (+)/HIF-1α (–) can sometimes be detected in cervix cancer samples." (PMID 37833987, 2023). "Based on luciferase assays, researchers found that the hypoxia-induced overexpression of HIF-1α activated the transcriptional activity of the PLAUR promoter, thereby enhancing its expression in cervical cancer, so that the cervical cancer cells were more invasive under hypoxic conditions." (PMID 35864968, 2022). "Higher expression of HIF1A and HIF3A could shorten the survival time of cervical cancer patients, indicating their oncogenic functions." (PMID 36277475, 2022). "Then, the expression of HIF-1α in transfected cervical cancer cells Siha and C33a was detected by qRT-PCR and Western blot, and the expression of YAP/TAZ was detected in cervical squamous cell carcinoma cells after HIF-1α expression was altered." (PMID 35664561, 2022). "As expected, MAC increased HIF-1α and BNIP-3 expression in cervical carcinoma cells." (PMID 36499465, 2022). "We analyzed the association between HIF-1α, YAP/TAZ, and clinical malignant phenotypes of cervical cancer, such as differentiation degree and lymph node metastasis, and analyzed the correlation between HIF-1α-positive expression and YAP/TAZ expression in cervical cancer tissues." (PMID 35664561, 2022). "Furthermore, HeLa-IRR and SiHa-IRR cells can increase glycolysis by increasing Hexokinase 2 (HK2), PKM, HIF-1α and GLUT-1 expression levels, and increase radiation resistance of cervical cancer cells." (PMID 35692795, 2022). "Several researchers showed that HIF-1α is overexpressed in HSIL and cervical cancer lesions." (PMID 36100684, 2022). "In this research, the expression and correlation of HIF-1α, YAP, and TAZ in normal cervical tissues, CIN and CSCC tissues, and cervical cancer cells were further detected by in vivo and in vitro assays, so as to further explore the roles of the three in the malignant progression of CSCC." (PMID 35664561, 2022). "In cervical cancer cells, OIP5-AS1 promotes IDH2 expression by inhibiting miR-124-5p, and IDH2 promotes the Warburg effect of cervical under hypoxic condition through regulating HIF-1α expression." (PMID 34513821, 2021). "Moreover, it was presented that HIF-1α accumulation is weakened by betulinic acid, leading to a diminution of HIF-1α responsive genes such as VEGF and GLUT1 in hypoxic cervical cancer cells." (PMID 34575983, 2021). "Since transforming growth factor- beta (TGF-β), SMAD3 and hypoxia inducible factor 1 alpha (HIF-1α) are upstream factors of DEC1, the DEC1 increases in cervical cancer cells may depend on their function under hypoxia and inflammation." (PMID 33089188, 2020). "It increases expression of the HIF1α in rat brain capillary endothelial cells and in mouse spinal-cord primary culture, and inhibits HIF1 activation in human hepatoma Hep3B cells, cervical carcinoma HeLa cells and aortic smooth-muscle cells." (PMID 32867129, 2020). "Furthermore, melittin showed anticancer and antiangiogenic effects by suppressing expression of hypoxia-inducible factor-1α (HIF-1α) and vascular endothelial growth factor (VEGF) through inhibition of ERK and mTOR pathways in human cervical cancer cells." (PMID 30866426, 2019). "Through its interaction with HIF-1a, HOTAIR is also able to induce radio-resistance in cervical cancer cells, suggesting that HOTAIR-HIF-1α axis might be a crucial mechanism for radio-resistance modulation hypoxia-induced." (PMID 31072041, 2019). "An HIF-1α-miR-21 positive feedback loop was observed through the PTEN/Akt/HIF-1α pathway whereby miR-21 decreased autophagy, resulting in increased radio-resistance in cervical cancer cells." (PMID 30266744, 2018). "B. HOTAIR and HIF-1α expression was upregulated in cervical cancer cells than normal cervical epithelial cells (NCECs)." (PMID 30355300, 2018).
cervical carcinoma (continued). "Whether mTOR, HIF-1α, and c-Myc are involved with PKM2 expression in cervical cancer patients receiving cisplatin-based NACT remains unclear." (PMID 27492148, 2016). "mTOR, HIF1α, c-Myc, and PKM2 expression in cervical cancer may serve as predictive biomarkers to cisplatin-based chemotherapy." (PMID 27492148, 2016). "Some clinical investigations have suggested that high expression of hypoxia-inducible factor-1α (HIF-1α) and/or its target gene carbonic anhydrase IX (CAIX) may be useful biomarkers of tumor hypoxia and poor outcome in cervical cancer." (PMID 26502718, 2015). "Furthermore, HIF-1α and VEGF165 genes, ROS were analyzed, and the results would provide new perspectives for the diagnosis and medical treatment of cervical cancer." (PMID 25905434, 2015). "Although HIF-1α expression may also be influenced by other pathways, a significant correlation between oxygen tension and HIF-1α has been reported in cervical cancer, suggesting that HIF-1α might be used as a surrogate for tumour hypoxia." (PMID 20492653, 2010). "Although the identified immune-related hub genes (HSP90AA1, CTNNB1, NPM1, HSPA5, and HIF1A) were significantly downregulated in HPV-positive cervical cancer, none of them demonstrated a statistically significant correlation with overall survival in the TCGA-CESC cohort." (PMID 41465546, 2025). "However, the relationship between HIF-1α (hypoxia-inducible factor 1) and Hippo pathway target gene Yes-related protein (YAP) and transcriptional coactivator (TAZ) in cervical carcinoma remains unclear." (PMID 35664561, 2022). "Some studies also found that HIF-1α is remarkably downregulated in cervical cancer tissues after chemotherapy compared with before chemotherapy, suggesting that HIF-1α can be used as a potential biomarker to predict the sensitivity of cisplatin chemotherapy in cervical cancer." (PMID 35795276, 2022). "However, the function of HOTAIR on radioresistance involving the regulation of HIF-1α in cervical cancer has not been reported." (PMID 30355300, 2018). "Therefore, we speculated that in cervical cancer cells, hypoxia upregulated HOTAIR expression to sponge miR-217, thus to promote HIF-1α expression." (PMID 30355300, 2018). "Although HIF-1α is strongly regulated by the oxygen tension in tumors and HIF-1 has multiple target genes promoting radiation resistance and malignant progression, the potential of HIF-1α as a biomarker of hypoxia and hypoxia-induced tumor aggressiveness in cervical carcinoma is controversial." (PMID 26502718, 2015). "The clinicopathological features and expression of HIF-1α, VEGF-A and Ki67 in cancer cells of pre-chemotherapy cervical cancer between chemotherapy response and nonresponse group." (PMID 37335690, 2023). "The expression of HIF-1α and VEGF-A proteins in the basal layer cells of adjacent normal and tissues tumor cells of cervical cancer pre- chemotherapy." (PMID 37335690, 2023). "Alternatively, although the difference was small, siRNA-mediated knockdown of HIF-1α, but not HIF-2α, increased TRAIL sensitivity in a prostate (DU145) and a cervical cancer cell line (HeLa)." (PMID 28476028, 2017). "In cervical cancer cell lines and HPV-transfected human foreskin keratinocytes, stabilization of HIF-1α protein levels under normoxia was not reported." (PMID 29163780, 2017). "Actually, we observed that knockdown of HIF-1α, but not HIF-2α, increased the TRAIL sensitivity of a prostate (DU145) and a cervical cancer cell line (HeLa)." (PMID 28476028, 2017). "We examined the tumor expression of mTOR, HIF-1α, c-Myc, and PKM2 in pre-chemotherapy cervical cancer tissues between chemotherapy responders and non-responders by immunohistochemistry." (PMID 27492148, 2016).
cervical carcinoma (continued). "However, the molecular mechanism of the interaction between HIF-1a and PD-L1 in the presence of HPV16 in cervical cancer has not been studied." (PMID 38257813, 2024). "However, others have found that HIF-1α and GLUT-1 were not correlated with MVD in patients with locally advanced cervical cancer." (PMID 28410229, 2017). "It is important to mention, however, that, as described in few studies, both HIF-1α and GLUT1 expression may not be quantitatively correlated to hypoxia in cervical cancer." (PMID 25296855, 2014).
Hyperglycemia (160 papers, 2008 to 2025). An increased concentration of glucose in the blood. "Hyperglycemia also affects hypoxia-inducible factor-1 alpha (HIF-1α) activity and is associated with metabolic disturbance and mitochondrial distress in cardiomyocytes." (PMID 41155741, 2025). "It has been demonstrated that hyperglycemia is associated with more aggressive form of certain cancers and higher level of HIF-1α expression." (PMID 40142263, 2025). "The excessive production of mitochondrial ROS is not only due to increased electron transport chain activity induced by hyperglycemia but also linked to impaired HIF-1α signaling." (PMID 39920720, 2025). "During myocardial ischemia/reperfusion, hyperglycemia reduced HIF-1α expression which was associated with enlarged infarction size." (PMID 37048134, 2023). "When diabetic female mice were crossed with males having a heterozygous-null mutation in the Hif1α gene, increased susceptibility to CHDs was observed in Hif1α+/− embryos exposed to maternal hyperglycemia compared with their WT littermates." (PMID 38003449, 2023). "High HIF-1α was significantly associated with more lymphovascular and peri-neural invasion, higher tumor regression score, less complete response, and hyperglycemia." (PMID 36011045, 2022). "We also confirmed that the high glucose environment activates the GLUT1-OGT-HIF-1α signal pathway causing 5-FU and radiation resistance, and hyperglycemia can induce HIF-1α expression by analyzing cancer specimens of mice with rectal cancer." (PMID 36011045, 2022). "Db/db mice with pressure ulcers showed an impairment in the molecular regulation of hypoxia-related genes (Hif1a, Flt1, and Kdr), while extracellular matrix encoding genes (Itgb3, Timp1, Fn1, Col4a1) were upregulated by hyperglycemia and lesions." (PMID 35386010, 2022). "HIF-1α is indispensable for normal embryonic development, and its decreased levels during hyperglycemia were associated with increased susceptibility to diabetic embryopathy." (PMID 36176990, 2022). "Hyperglycaemia is known to cause HIF-1α dysfunction and the impairment of bone formation in diabetic patients." (PMID 35977987, 2022). "For example, HIF-1α-mediated regulation of the NLRP3/IL-1β signalling pathway has been reported to play a role in susceptibility to pulmonary aspergillosis in a hyperglycaemia mouse model." (PMID 36275017, 2022). "The HIF-1A Pro582Ser polymorphism confers resistance to hyperglycaemia-mediated inhibition of HIF-1 activity and protects against the development of diabetic nephropathy, severe diabetic retinopathy and diabetic foot ulcers." (PMID 33496820, 2021). "Although the molecular mechanism of this relationship is still unclear, researchers have come to an agreement that hyperglycemia is directly linked to a compromised HIF-1a expression level." (PMID 34394393, 2021). "Recent work has shown that the HIF-1A Pro582Ser polymorphism is more resistant to hyperglycemia-mediated repression, thus protecting against the development of diabetic nephropathy." (PMID 31214621, 2019). "As shown in a previous work by our group, the protein stability of the HIF-1α Pro582Ser polymorphism was also diminished in the presence of hyperglycemia." (PMID 31214621, 2019). "In comparison, loss of myeloid HIF-1α not only protected against the initial hyperglycemia but caused a significant delay in the development of hypoglycemia." (PMID 30524296, 2018). "Besides this, hyperglycemia causes activation or overexpression of some protooncogenes, including hypoxia-inducible factor-1α (HIF1-α), AKT, mammalian target of rapamycin (mTOR), and c-myc." (PMID 39812937, 2025). "In addition to hypoxia, numerous metabolic stressors associated with DM, including hyperglycemia, affect HIF-1α stabilization and activity." (PMID 37305566, 2023). "The in vivo results indicated that hyperglycemia could induce HIF-1α expression and cause rectal cancer radioresistance." (PMID 36011045, 2022).
Hyperglycemia (continued). "Although the findings confirm the association of hyperglycemia, HIF-1a, and CCRT efficacy in rectal cancer patients, the population of this study is too small and the number of cases received needs to increase to more accurately confirm the association between the factors." (PMID 36011045, 2022). "An increase in basal HIF-1α mRNA expression has also been observed in hearts of diabetic rats as well as in isolated non-diabetic rat hearts perfused with high glucose under non-hypoxic condition, confirming a pseudohypoxic state caused by hyperglycemia." (PMID 33520443, 2021). "Moreover, we have brought further mechanistic insight into the function of the HIF-1A Pro582Ser polymorphism in hyperglycemia." (PMID 31214621, 2019). "In previous work, we found that the HIF-1A Pro582Ser polymorphism was protective for diabetes nephropathy by conferring a relative resistance of the encoded HIF-1α to the repressive effects of hyperglycemia on the transactivation level." (PMID 31214621, 2019). "In this study, we have investigated the effect of the HIF-1A Pro582Ser polymorphism on the development of DR and further dissected the mechanisms by which the polymorphism confers a relative resistance to the repressive effect of hyperglycemia." (PMID 31214621, 2019). "Indeed, both hyperglycaemia and low glucose concentrations have been implicated in the regulation of HIF1α expression and stability." (PMID 29985416, 2018). "Hyperglycemia causes hypoxia, but also affects the function of HIF-1α." (PMID 30158902, 2018). "Furthermore, HIF-1 signaling has been demonstrated to be downregulated in diabetes due to hyperglycemia-induced HIF-1α destabilization linked to functional inhibition." (PMID 27084094, 2016). "Additionally, maternal hyperglycemia alters, directly or indirectly via oxidative stress, important molecular pathways implicated in cardiac development, notably the Wnt, Notch, TGFβ, NO, and Hif1α pathways." (PMID 38003449, 2023). "Finally, we looked at whether inhibition of HIF-1α could reduce hyperglycemia and cause the radiation tolerance of rectal cancers." (PMID 36011045, 2022). "In DFU, however, due to hyperglycaemia and oxidative stress, reduced HIF-1α stability ensues, resulting in reduced neovascularization and, eventually, poor tissue repair." (PMID 40708812, 2025). "Accordingly, a glucagon-dependent hyperglycaemia is described as promoting cancer progression and angiogenesis under the activation of HIF1α pathways, which is the main controller of glycolysis." (PMID 40649254, 2025). "Chronic hyperglycemia can disrupt oxygen homeostasis, resulting in tissue hypoxia, leading to downregulating the hypoxia-inducible factor-1α (HIF-1α)." (PMID 40271074, 2025). "Compared to hypoxia, our results revealed a minor role of hyperglycemia regarding a potential effect on the expression of HIF1A and its AS lncRNAs in HK-2 cells." (PMID 40739162, 2025). "In the retina and kidneys, persistent HIF-1α activation under chronic hyperglycemia promotes pathological angiogenesis and fibrosis, contributing to diabetic retinopathy and nephropathy." (PMID 40867634, 2025). "We first discovered that exposure to 33 mM glucose and 1% O2 induced hypoxia accompanied by overexpression of hypoxia-inducible factor-1α (HIF-1α), indicating the effect of hyperglycemia on hypoxia." (PMID 38310127, 2024). "SET7/9 is a crucial regulator in the regulation of hypoxia-inducible factor-1α (HIF-1α) methylation and the activation of HIF-1α target genes involved in the processes of angiogenesis and wound healing, particularly in situations of hypoxia and hyperglycemia." (PMID 39229271, 2024). "Hyperglycemia promotes ubiquitination of the carboxy-terminus of HIF-1α ligase and subsequent proteasomal degradation, thereby destabilizing HIF-1α." (PMID 39720256, 2024).